CD4 (CD4 molecule)
Diseases named in the same sentence as CD4 in open-access papers (continued):
Sharing a sentence is not in itself a finding about the gene and the disease.
polycystic ovary syndrome (8 papers, 2018 to 2025). A disorder that manifests as multiple cysts on the ovaries. "Unfortunately, there has been very limited research conducted on the CD4+CD28null T lymphocyte subset in animal models of hyperandrogenemia and PCOS." (PMID 37109539, 2023). "Impaired function of both CD4 + and CD8 + T cells and abnormal cytokine production is also associated with polycystic ovarian syndrome (PCOS)." (PMID 37408003, 2023). "Combined with our results, although research on LOC100507250 is very limited, it is our speculation that LOC100507250 may interact with immune lymphocytes, especially gamma delta T cells and activated CD4 memory T cells, involving in the pathological process of polycystic ovary." (PMID 36118901, 2022).
post-traumatic stress disorder (8 papers, 2013 to 2025). An anxiety disorder precipitated by an experience of intense fear or horror while exposed to a traumatic (especially life-threatening) event. "A 2016 study of individuals in Detroit, Michigan found that individuals who experienced post-traumatic stress disorder (PTSD) in the past year showed a shift in the distribution of T cells favoring CD8+ cells over CD4+ cells, and effector memory CD8+ cells over naïve CD8+ cells." (PMID 39006475, 2024). "The downstream negative effects of violent traumas, particularly IPV, are apparent on mental health (i.e., depression, post-traumatic stress disorder (PTSD), SUDs), and HIV-related outcomes (i.e., CD4, viral load, opportunistic infections, AIDS mortality)." (PMID 38384880, 2024). "The posttraumatic stress disorder symptoms could predict the medication non-adherence and lower CD4 levels." (PMID 30847322, 2019).
primary sclerosing cholangitis (8 papers, 2000 to 2026). "identify the primary sclerosing cholangitis-associated genetic polymorphism rs56258221 to enhance miR4464 expression in naive CD4+ T cells." (PMID 38901430, 2024). "The number of CD4 Treg cells in biliary tissue correlates with tissue IgG+ plasma cells in IgG4-related sclerosing cholangitis, and circulating CD4 Treg cells correlate with serum IgG4 in autoimmune pancreatitis." (PMID 39051325, 2024). "Sclerosing cholangitis was reported later and further immunological investigation revealed low percentages of CD4+ T cells and low serum IgM levels." (PMID 36703986, 2022). "Recently, the expansion of liver-resident CD4+T naïve-like cells (CD4+TLR-NL) acquiring a TH17 polarization state has been proven to be a candidate contributor to primary sclerosing cholangitis (PSC) pathogenesis." (PMID 36569318, 2022). "Only recently the analysis of CD4+CD28− T cells in patients with primary sclerosing cholangitis revealed that these cells occur with a frequency of 3,3% of all CD4+ T cells in the peripheral blood and 30,3% in the liver tissue, where they accumulate around the bile ducts." (PMID 25834833, 2015). "Amongst the chemokine receptors, CX3CR1 on the surface of CD4+CD28− T cells is best characterised in the peripheral blood of RA, MS, and primary sclerosing cholangitis patients." (PMID 25834833, 2015).
rheumatic heart disease (8 papers, 2017 to 2025). An autoinflammatory condition following an infection with Group A Beta Hemolytic Streptococcus (GABHS), in which the heart is attacked by antibodies formed in reaction to a recent GABHS infection. "Furthermore, USP4 targeted on TGFβ-activated kinase 1 (TAK1) to downregulate NF-κB activation, which was highly expressed in CD4+ T cell from rheumatic heart disease." (PMID 34177595, 2021). "Studies found that CD4+ T lymphocytes and the TGF‐β1/MAPK signaling pathway are involved in valve tissue hyperplasia and fibrotic lesions in rheumatic heart disease." (PMID 35535387, 2022). "In patients with rheumatic heart disease (RHD), an autoimmune disease, USP4 was found to be significantly elevated in CD4+ T cells." (PMID 33681193, 2021). "Thus, the drug increased the levels of CD3+ cells and activated CD69 cells in bronchial asthma, and the levels of CD3+, CD4+ and CD8+ T-lymphocytes in chronic rheumatic heart disease." (PMID 41463008, 2025). "Additionally, CD4+ T cells and the TGFβ1/MAPK pathway have been identified as contributors to valvular hyperplasia and fibrosis in individuals with rheumatic heart disease." (PMID 39421157, 2024).
septic arthritis (8 papers, 2016 to 2025). "Thus, it appears that CD4+ T cells are pathogenic during S. aureus septic arthritis due to their ability to produce proinflammatory cytokines such as TNF-α and IFN-γ via activated macrophages." (PMID 33546401, 2021). "Similarly, depletion of CD4+ but not CD8+ cells significantly reduced the severity and frequency of bone erosions in P. aeruginosa-induced septic arthritis, strongly indicating that CD4+ T cells are pathogenic in this disease." (PMID 31727989, 2019). "Thus, to further address the mechanism underlying the outcome of ST2 deficiency in septic arthritis, it was next performed a flow cytometry gating CD4+IFN-γ+T cells and CD4+IL-4+T cells at the 7th and 14th day post-infection in LNs cells." (PMID 29867945, 2018). "CD4+ T cells are known to be pathogenic in the course of S. aureus arthritis in mice, and pretreatment with anti-CD4 antibodies attenuated the severity of S. aureus septic arthritis in mice." (PMID 26787717, 2016). "Finally, CD4+ T-cells are pathogenic in P. aeruginosa septic arthritis." (PMID 31727989, 2019). "The significance of CD4 T cells and V beta 11+ T cells in the development of septic arthritis has been established." (PMID 38410388, 2024). "This suggests that CD4 T cells and V beta 11+ T cells play a crucial role in the pathogenesis of septic arthritis in this experimental setting." (PMID 38410388, 2024). "The index patient in this study had polyarticular septic arthritis, which should also be suspected in patients having a CD4+T cell count of less than 200 cells/mm3." (PMID 39735158, 2024). "Recent results also found that CD4+ T cells promote the pathogenesis of S. aureus pneumonia and Pseudomonas aeruginosa septic arthritis." (PMID 33546401, 2021). "Next, we investigated the role of T-cells in P. aeruginosa-induced septic arthritis by selectively depleting either CD4 or CD8 T-cells in the mice." (PMID 31727989, 2019). "Interestingly, depletion of CD4+ T cells diminished the arthritogenic outcome, hence indicating that CD4+ T cells provoke septic arthritis severity, whereas depletion of CD8+ T cells displayed a tangible effect on the severity of the disease." (PMID 41170422, 2025). "Nonspecific innate immune responses, including neutrophils and NK cells, are generally considered to be protective against septic arthritis, whereas certain cell types, e.g., CD4+ T cells of the acquired immune system, potentiate the severity of disease by triggering exaggerated responses." (PMID 26787717, 2016). "Thus, increasing CD4+IL-10+T+ cells and IL-10 production at later time points in the course of septic arthritis at which the infection was already controlled could be a mechanism to reduce joint inflammation in ST2−/− mice." (PMID 29867945, 2018). "Consistent with the inability of WT mice in controlling the infection, these mice showed Th2 profile in septic arthritis with high-IL-4/CD4+T cell and low-IFN-γ/CD4+T cell counts." (PMID 29867945, 2018). "Furthermore, depletion of CD4+ cells significantly ameliorates the course of septic arthritis in mice, whereas depletion of CD8+ T cells does not alter the course of arthritis compared to control mice." (PMID 33546401, 2021).
small cell lung carcinoma (8 papers, 2015 to 2025). Small cell lung cancer (SCLC) is a highly aggressive malignant neoplasm, accounting for 10-15% of lung cancer cases, characterized byrapid growth, and early metastasis. "In contrast, apCAFs exert tumor-suppressive effects by producing C1q in small cell lung cancer, which binds to the C1qbp on the surface of CD4+ effector T cells, preventing their apoptosis." (PMID 39891284, 2025). "Further predictive accuracy was achieved by DC and TMB in combination with CD4+ naive T-cells abundance, and then validated in the small cell lung cancer cohort." (PMID 36505471, 2022). "In contrast, high CD4+/CD8+ ratio due to high percentage of CD4+ cells in tumors have been correlated with lymph nodes metastasis and reduced patient survival in breast, renal, esophageal and small cell lung carcinomas." (PMID 25605488, 2015). "In conclusion, the sensitized specific T cells in the PBMCs of PNS patients predominantly comprised of CD4+ T cells, which had no inhibitory effect on small cell lung cancer cells in vitro." (PMID 25412252, 2015).
T-cell neoplasm (8 papers, 2015 to 2024). "Coexpression of CD2, CD4, CD7, and CD30 by the mast cells particularly in skin lesions may provoke misinterpretation as a cutaneous T-cell neoplasm." (PMID 31772790, 2019). "Malignancy-specific immunophenotypic abnormalities in CD4+/CD8− T-cells (e.g., conspicuously dim expression of CD2, CD3, CD4, CD5, or CD45; or conspicuously increased light scatter) should further prompt strong consideration of a T-cell neoplasm in the appropriate clinical setting." (PMID 33673033, 2021).
thyrotoxicosis (8 papers, 2018 to 2026). A hypermetabolic syndrome caused by the elevation of thyroid hormone levels in the serum. "The present case fits this pattern: after a nadir CD4 count of 23 cells/mm3 and robust immune recovery (CD4 >1800 cells/mm3), thyrotoxicosis developed 33 months into ART." (PMID 41551367, 2026). "Compared with the normal control group, the percentage of CD3+CD4+ in thyrotoxicosis mice decreased significantly, while the percentage of CD3+CD8+ increased significantly, so the percentage of CD4+/CD8+ decreased significantly." (PMID 35720307, 2022). "The results of flow cytometry showed that the RSGB treatment significantly increased the ratio of CD4+/CD8+ and the percent CD3+CD4+ IFN-γ+ in thyrotoxicosis mice." (PMID 36389720, 2022). "The results of routine blood tests and flow cytometry showed that immunosenescence occurred in thyrotoxicosis mice, which was characterized by a significant decrease in neutrophils, lymphocytes, CD4+/CD8+ and CD4+IFN-γ+ lymphocytes." (PMID 35720307, 2022). "The percentage of CD3+CD4+ IFN-γ+ was significantly decreased in thyrotoxicosis mice." (PMID 35720307, 2022). "RSGB significantly improved immunosenescence in thyrotoxicosis mice, which was manifested in increasing the total number of leukocytes, neutrophils, lymphocytes, and the percent of CD4/CD8 and CD3+CD4+ IFN-γ+." (PMID 36389720, 2022). "The flow cytometry test showed a decrease in CD4/CD8 ratio and the number of CD4+IFN-γ+ T cells in thyrotoxicosis mice, which indicated that immunosenescence occurred." (PMID 35720307, 2022). "A statistically significant negative correlation was found between the level of CD4/CD25 and both T3 and T4, indicating the relation between the level of Treg cells and the disturbance that occurs in the thyroid function abnormalities in cases of thyrotoxicosis." (PMID 41307767, 2025).
uveal melanoma (8 papers, 2019 to 2024). A melanoma derived from melanocytes of the uveal tract. "Finally, Mel202/DR1/CD80 uveal melanoma vaccine cells expressed the intercellular adhesion molecule 1 (ICAM-1) that was pivotal for CD4+ T cell activation via lymphocyte function-associated antigen 1(LFA-1)." (PMID 30956760, 2019). "The levels of NQO1 mRNA were negatively correlated with CD4 T cells and CD8 T cells in testicular germ cell tumors and positively associated with CD4 T cells and CD8 T cells in uveal melanoma and ovarian serous cystadenocarcinoma." (PMID 37583897, 2023). "The present data demonstrate that MHCII primary uveal melanoma vaccines directly prime and boost a diverse repertoire of purified CD4+ T cells." (PMID 30956760, 2019). "The vaccine cells were able to activate CD4+ T cells that react with primary uveal melanoma cells and cross-react with metastatic uveal melanoma cells." (PMID 30956760, 2019). "Previously, we showed that these uveal melanoma cell-based vaccines activate CD4+ T cells within total peripheral blood lymphocytes (PBMC)." (PMID 30956760, 2019). "We are exploring immunotherapeutic options for metastatic uveal melanoma using MHC II uveal melanoma cell-based vaccines that target the activation of tumor-reactive CD4+ T cells." (PMID 30956760, 2019). "Collectively, our data indicate that Mel202/DR1/CD80 uveal melanoma vaccine cells maintain the activation of various subtypes of CD4+ T cells." (PMID 30956760, 2019). "Therefore, the ICAM-1/LFA-1 interaction plays an important role in the activation of CD4+ T cells by Mel202/DR1/CD80 uveal melanoma vaccines." (PMID 30956760, 2019). "In conclusion, MHC II uveal melanoma vaccines activate purified CD4+ T cells and may serve as a novel immunotherapy for uveal melanoma patients." (PMID 30956760, 2019). "A positive correlation was observed between CD24 expression levels and the infiltration of activated CD8+ T cells, activated CD4+ T cells, natural killer cells, activated dendritic cells, macrophages, monocytes, and neutrophils in SKCM, uveal melanoma (UVM), adrenocortical carcinoma (ACC), and UCS." (PMID 39791710, 2024). "Additionally, MHC II has been shown to activate tumor-specific CD4 + and CD8 + T cells, promoting immunogenicity in uveal melanoma." (PMID 37189078, 2023). "Since the antigens presented by the uveal melanoma vaccine cells are unknown, we determined TCR-Vβ usage of vaccine-activated CD4+ T cells upon repetitive stimulation with Mel202/DR1/CD80 vaccines." (PMID 30956760, 2019). "Development of metastasis was associated with a decrease of peripheral DN and CD8+CD56+ T-cells, whereas the frequency of CD4+CD56+ T-cells was not altered, suggesting a potential involvement of DN and CD8+CD56+ T-cells in cancer immunosurveillance in uveal melanoma." (PMID 31419253, 2019).
viral pneumonia (8 papers, 2020 to 2025). Inflammation of the lung parenchyma that is caused by a viral infection. "Actually, different changes in CD4+/CD8+ ratio is a reflection to the immune function in different stages of viral pneumonia." (PMID 38811907, 2024). "AMPKα1 is required for bulk CD4+ T cell expansion in the lung during viral pneumonia, but whether AMPKα1/α2 are necessary for Treg cell function in this context is unknown." (PMID 40100289, 2025). "There are also reports revealing the ratio of CD4+/CD8+ T cell decreased in viral pneumonia, which may be due to the suppression of CD4+ T cells, the decrease in the absolute number of lymphocytes, and the activation of cytotoxic CD8 + T cells." (PMID 38811907, 2024). "This study mainly focuses on the immune function and introduces CD4+, CD8+ T cells and their ratios based on the MuLBSTA score, a previous viral pneumonia mortality risk warning model, to construct an early warning model of severe viral pneumonia risk." (PMID 38811907, 2024). "In this study, the number of CD4+ and CD8+ T cells in patients with severe and critical viral pneumonia were significantly decreased." (PMID 38811907, 2024).
xerostomia (8 papers, 2013 to 2023). Dryness of the mouth resulting from reduced salivary secretion. "Dysgeusia and xerostomia of diverse severity have also been documented, especially under anti-PD-1/PD-L1 treatment, and they are attributed to CD4/CD8-T-cell toxicity against the salivary glands." (PMID 37370736, 2023). "Other parameters collected show that HIV+ persons in the current cohort had less OPC, less antifungal use, higher blood CD4 cell counts, and a lower incidence of xerostomia, across age, race, and sex, compared to the previous HIV+ cohort." (PMID 37401527, 2023). "Some risk factors triggering periodontitis include passive tobacco consumption, diabetes, CD4+ T lymphocyte count <200 cells/μL, and xerostomia, among others." (PMID 36143891, 2022). "Co-expression levels of PD-1, CXCR5, CD4, CCR2, and CCR5 in the salivary gland specimens from patients with pSS and patients with dry mouth and eyes but normal pathology were also analyzed." (PMID 35755031, 2022). "Sjögren syndrome (SS) is an autoimmunity-driven chronic infammatory disorder, characterized by infiltration and destruction of lacrimal and salivary glands by effector CD4+ and CD8+ T cells and activated macrophages, resulting in keratoconjunctivitis with dry eyes and xerostomia (dry mouth)." (PMID 24027536, 2013).
African trypanosomiasis (7 papers, 2009 to 2023). "Moreover, IFN-γ production by variant surface glycoprotein-specific CD4 T cells has been known to be important for both control of (early stages), and susceptibility to (late stages), infection with African trypanosomiasis." (PMID 30619253, 2018). "Several reports have shown that CD4+CD25+Foxp3+ Tregs play disease-promoting role in experimental African trypanosomiasis." (PMID 28769924, 2017). "IFN-γ, mainly secreted by VSG-specific CD4+ T cells following activation by dendritic cells, has been shown to mediate protection during African trypanosomiasis." (PMID 26222157, 2015). "Obviously, IL-27 signaling functions through limiting activation of CD4+ T cells in African trypanosomiasis." (PMID 26222157, 2015). "The natural Treg cells, CD4+CD25highFoxp3+ were recently studied in experimental model of African trypanosomiasis in Trypanosoma congolense - infected mice." (PMID 19584913, 2009). "Obviously, in the absence of IL-27 signaling, excessive secretions of IFN-γ by CD4+ T cells also mediate liver pathology and mortality, although IL-10 signaling still fully functions and the infected mice produce even more IL-10, in African trypanosomiasis." (PMID 26222157, 2015). "The protective role of CD4+ T cells and IFN-γ in African trypanosomiasis has been recently confirmed by independent groups." (PMID 26222157, 2015).